PEDS1-UBE2V1 (PEDS1-UBE2V1 readthrough)
Synonyms: Kua-UEV; CROC-1B; CROC1B; TMEM189-UBE2V1
Gene: Protein-coding gene on chromosome 20 (50,081,124 to 50,153,637, reverse strand). Ensembl gene ENSG00000124208.
Genetic constraint (gnomAD): Loss-of-function variants: 21 observed, 41.55 expected, observed/expected ratio (o/e) 0.51, 90% interval 0.36 to 0.73. The upper end of that interval is the gene's LOEUF score, 0.73, which puts it in group 2 of 6, group 1 being the genes least tolerant of losing a copy. Missense variants: 268 observed, 446.8 expected, observed/expected ratio (o/e) 0.6, 90% interval 0.54 to 0.66. Synonymous variants: 164 observed, 168.12 expected, observed/expected ratio (o/e) 0.98, 90% interval 0.86 to 1.11.
Diseases named in the same sentence as PEDS1-UBE2V1 in open-access papers:
PEDS1-UBE2V1 is named in the same sentence as 1 disease in open-access papers, as found by Europe PMC text mining. Sharing a sentence is not in itself a finding about the gene and the disease.
PEDS1-UBE2V1 shares sentences with these, for which no sentence is quoted: ovarian carcinoma (1 paper).